CLPX (caseinolytic mitochondrial matrix peptidase chaperone subunit X)
Description:
ATP-dependent chaperone that functions as an unfoldase. As part of the ClpXP protease complex, it recognizes specific protein substrates, unfolds them using energy derived from ATP hydrolysis, and then translocates them to the proteolytic subunit (CLPP) of the ClpXP complex for degradation. Thanks to its chaperone activity, it also functions in the incorporation of the pyridoxal phosphate cofactor into 5-aminolevulinate synthase, thereby activating 5-aminolevulinate (ALA) synthesis, the first step in heme biosynthesis. This chaperone is also involved in the control of mtDNA nucleoid distribution, by regulating mitochondrial transcription factor A (TFAM) activity.
Synonyms: EPP2
Tractability: PROTAC: ubiquitination databases record sites on it; its protein half-life has been measured; a small molecule that binds it is known.
Target class: Enzyme
Gene: Protein-coding gene on chromosome 15 (65,148,219 to 65,185,393, reverse strand). Ensembl gene ENSG00000166855.
Subcellular location: Mitochondrion; Mitochondrion matrix, mitochondrion nucleoid
Subcellular location (Human Protein Atlas): Mitochondria; Cytosol; Equatorial segment; Nucleoplasm; Perinuclear theca
Pathways (Reactome):
Metabolism of proteins: Mitochondrial protein degradation
Gene Ontology:
Molecular function: ATP hydrolysis activity; ATP-dependent peptidase activity; peptidase activator activity; protein binding; ATP binding; ATP-dependent protein folding chaperone
Biological process: ATP metabolic process; protein catabolic process; proteolysis; protein folding
Cellular component: endopeptidase Clp complex; mitochondrial endopeptidase Clp complex; mitochondrial matrix; mitochondrial nucleoid; mitochondrion; mitochondrial inner membrane
Genetic constraint (gnomAD): Loss-of-function variants: 18 observed, 45.54 expected, observed/expected ratio (o/e) 0.4, 90% interval 0.27 to 0.59. The upper end of that interval is the gene's LOEUF score, 0.59, which puts it in group 2 of 6, group 1 being the genes least tolerant of losing a copy. Missense variants: 432 observed, 544.58 expected, observed/expected ratio (o/e) 0.79, 90% interval 0.73 to 0.86. Synonymous variants: 174 observed, 201.56 expected, observed/expected ratio (o/e) 0.86, 90% interval 0.76 to 0.98.
Homologues: Orthologues: chimpanzee CLPX (99% identical), macaque CLPX (99% identical), dog CLPX (98% identical), pig CLPX (98% identical), mouse Clpx (96% identical), guinea pig CLPX (95% identical), rat Clpx (94% identical), rabbit CLPX (89% identical), tropical clawed frog clpx (86% identical), zebrafish clpxa (83% identical), zebrafish clpxb (79% identical), Drosophila melanogaster ClpX (57% identical), and 1 more.